CD4 (CD4 molecule)
Diseases named in the same sentence as CD4 in open-access papers (continued):
Sharing a sentence is not in itself a finding about the gene and the disease.
infection (continued). "We have not yet quantified the epitope display on MHC class II positive cells in the lung at later time points when CD4 T cells begin to infiltrate the lung (day 5–6 postinfection) or the presence long lived antigen depots in this infection system." (PMID 29681900, 2018). "Collectively, these studies indicate that rationally designed TB vaccines should generate immune responses that prevent the establishment of infection and/or provide sterilizing immunity by inducing both lung CD4+ TRM and CD8+ TRM in the lungs." (PMID 30038624, 2018). "Granulomas are a sign for control of infections and are composed of macrophages and giant multinucleated cells that contain cryptococcal cells, as well as CD4+ T-cells." (PMID 29670625, 2018). "The binding of viral envelope glycans to L-selectin facilitates HIV entry and infection, and L-selectin expression on central memory CD4+ T cells supports their preferential infection by HIV." (PMID 30026537, 2018). "Levels of cis infection controls of CD4+ T cells alone with the low MOI used for trans infection experiments were very low or undetectable in all clinical groups." (PMID 29643243, 2018). "Studies have reported high levels of ISG expression in CD4 T cells very early during infection, and increased levels of APOBEC3G was found to correlate with lower levels of infection in macrophages during SIV infection." (PMID 29520278, 2018). "Adjustment for relative CD4+ T lymphocyte levels prior to infection for each individual animal yielded consistent results for the duration of infection." (PMID 29437924, 2018). "The increase of T CD8+ cells was massive and persistent at the three post-infection time points tested, whereas the increase of T CD4+ was lower and significant solely at 10 dpi (although 4/7 birds were still high at 14 dpi)." (PMID 29587836, 2018). "In contrast, the infection induces a potent immune response in the skin mediated by CD4+ T cells, which have an effector phenotype that preferentially produce interferon gamma (IFN-γ) and mediate a transitory DTH reaction." (PMID 29946313, 2018). "We carried out aerosol infection of C57BL/6 mice with Erdman, and, 6–8 weeks post infection, we purified polyclonal CD4+ or CD8+ T cells from their lungs and co-cultured them with Mtb-infected macrophages." (PMID 29782535, 2018). "Among the hu-CD3+ T-cells, the frequency of activated CD4+CD25+ T-cells increased gradually up to 5 weeks after infection in the peripheral blood of both WT and ΔPBM hu-mice, while at 7 weeks this percentage was significantly higher in WT than in ΔPBM hu-mice." (PMID 29566098, 2018). "First, WNV lethality increases with age in both mice and humans, so we wanted to know if this was related to changes in the number of WNV-specific CD4+ T cells that expand upon infection." (PMID 29864157, 2018). "Tissue immune-phenotyping further revealed higher levels of infiltration of neutrophils and possibly CD4+ T cells into the joint footpad at 6 days post-infection (dpi) during enhanced CHIKV infection." (PMID 29382880, 2018). "Although much of this review focuses on findings generated in mouse models of infection or autoimmunity, we specifically highlight important observations made on human CD4 TRM throughout the manuscript." (PMID 30386342, 2018). "The importance of CD4+ T cells in controlling infection is critical, and all antigens selected also induced CD4+ T cell responses." (PMID 29661928, 2018). "Heterologous infections have been shown to alter epitope immunodominance, CD4+ T cell Th1/Th2 ratio, cytokine levels (e.g., TNF-α), and augment expression of antigen presentation and co-stimulatory molecule expression on APCs." (PMID 29872429, 2018). "A further key question that remains to be addressed is the consequences of reactivation of memory CD4 T‐cells by B‐cells within either ELS or immune cell clusters at the infection site itself." (PMID 29570776, 2018).
infection (continued). "Note that cofilin activation is particularly important for infection of resting CD4+ T-cells, which have predominantly inactive cofilin and low levels of endocytosis." (PMID 29401736, 2018). "We therefore compared the expression levels of HK1, HK2, and VDAC in HIV-1 infected and uninfected CD4+ T cells at 24 and 48 h after infection." (PMID 29518929, 2018). "While CD4+CD134+ cells represent the primary cell type infected during acute FIV infection, the expansion of this population during PLV infection did not result in higher viral loads following FIV exposure." (PMID 29677149, 2018). "Together, these data show that IL-27 is produced by multiple DC subsets (i.e. pDCs, CD11b+ and CD8+ cDCs) after MCMV infection and that DC-derived IL-27 is required to restrict a cytotoxic phenotype in antiviral CD4 T cells upon infection." (PMID 30044874, 2018). "We found moDC-to-CD4+ T cell infection was at least 2-fold more insensitive to TFV or RAL at moDC-to-CD4+ T cell ratios of 1:1 and 1:8, but not 1:32." (PMID 29293546, 2018). "While the ratio beyond day 12 post infection remains to be seen, it is clear that not only the quality but also quantity of CD4+ TH cells is also important during infection." (PMID 29616390, 2018). "Briefly, we added cell and viral populations and interactions that capture the basic processes: infection of CD4+ T cells by HIV-1, conversion of these cells into those which actively produce HIV-1, and the production and decay of extracellular virus." (PMID 29698393, 2018). "Within the CD4+ T-cell population, the frequency of effector memory T-cells increased during the ongoing infection both in CQ-RAS or CQ-CPS immunized animals." (PMID 29449638, 2018). "The major cellular source of IL-13 changes from the CD4+ T cell at day 21 after infection to macrophages at 7 weeks after infection." (PMID 30513770, 2018). "Taken together, these data show that MΦ derived from NP do not efficiently transfer HIV-1 to autologous CD4+ T cells, which are capable of supporting HIV-1 CD4+ T cis infection, in accordance with our previous DC and B cell results." (PMID 29643243, 2018). "Our IL-10+IL-21+ CD4-depletion experiments indicate that early inflammatory signals propagated during the first few weeks of LCMV Cl13 infection are necessary for the formation of IL-10+IL-21+Tfh cells." (PMID 30487586, 2018). "Lung-resident memory CD4 T cells are primarily identified by CD69 expression following infection or vaccination." (PMID 30233573, 2018). "Our results are consistent with these observations and demonstrate that treatment with RvD2 reduces the frequency of CD4+ T-cells and Foxp3+CD4+ Treg cells in the gingiva 6 weeks after infection." (PMID 29922275, 2018). "For epidemiological studies and public health monitoring, CD4+ cell count at diagnosis is the most commonly used biomarker to assess the likely delay from infection to diagnosis." (PMID 29945571, 2018). "Our metric for virus-dependent selection was calculated by dividing the proportion of ΔCCR5 CD4+ T-cells in each animal during productive infection by the same value measured prior to productive infection." (PMID 29672640, 2018). "Nevertheless, DC were found to sequester virus for several days before efficiently spreading the infection to CD4+ T-cells." (PMID 29415518, 2018). "After infection CD4+ T cells undergo activation manifested by expression of surface molecules including HLA-DR and CD38." (PMID 30409122, 2018). "While information on timing of infection can be used to assist inference of directionality, only weekly informative data in the form of CD4+ counts were available." (PMID 30027754, 2018). "Early studies on transmitted/founder (T/F) HIV-1 have suggested that CD4+ T cells serve as the main target cells in the establishment of HIV-1 early infection." (PMID 30619292, 2018).
infection (continued). "Mice lacking CD4+ T cells initially clear infectious SFV at the same rate as WT controls, this corroborates a study on the early stage of infection in SINV infected CD4 knockout mice." (PMID 29783708, 2018). "A central component of iBALT in this model is the presence of CXCR5+ CD4 T cells which are initially recruited during the effector phase of infection." (PMID 30386342, 2018). "By removing MHC II from infected myeloid cells, M78 isolated them from any CD4+ T cell engagement, promoting systemic infection spread and making MCMV-infected cells harder for CD4+ T cell-dependent defences to find." (PMID 29447285, 2018). "Several factors have been associated with the development of neutralization breadth, including duration of infection, high viral load, low CD4 count, genetic subtype and viral diversity." (PMID 29630668, 2018). "HIV-1 cis-infection and trans-infection of CD4+ T target cells from DCs have been proposed to be mediated by distinct processes." (PMID 29515578, 2018). "As with the CD8+ TRM cells, local antigen also plays a role, as late antigen recognition at day 5–8 post-infection, which has been termed a “memory check point,” is necessary for the formation of memory CD4+ T cells in the lung and spleen." (PMID 29904388, 2018). "(B) Representative experiment of HIVGKO virus titration in activated primary CD4+ T cells (4 days post-infection)." (PMID 29714165, 2018). "Under these conditions, MΦ-mediated trans infection was undetectable in all NP tested throughout the 12 days of coculture, while MΦ from PR were able to trans infect autologous CD4+ T cells." (PMID 29643243, 2018). "Infection with Cytomegalovirus results in approximately 10% of the CD4+ and CD8+ T cell pool becoming specific for this virus, although large inter-individual differences exist." (PMID 29713319, 2018). "For example, CD4+ memory T cells can be detected in the liver many months after Lm infection and tissue-homing and/or tissue-resident CD4+ memory T cells have been characterized for a variety of infections in the lung, skin and reproductive tract." (PMID 29438281, 2018). "Each CD8+ or CD4+ T cell responses are sufficient in providing sterilizing immunity and dissolution of foci of infection." (PMID 29862325, 2018). "The proportion of CD3+CD4+CD161+ T cells was lower in patients who developed infection before engraftment (5.28 ± 0.60% versus 7.32 ± 0.83%, P = 0.045) and CMV reactivation (4.46 ± 0.61% versus 6.74 ± 0.63%, P = 0.041)." (PMID 29511683, 2018). "This persistence was associated with histopathological changes, accompanied by augmented numbers of BM myeloid GMP progenitors, PMNs, and CD4+ lymphocytes during the acute phase (eight days) of the infection in the BM." (PMID 30622977, 2018). "In this study, we investigated the role of CD4+T cells in protection from ZIKV using a mouse model of infection." (PMID 30212537, 2018). "The negative correlations between the number of CTL escapes in pol and lower CD4/CD8 ratio were confirmed also when only the recent infections were analysed (1.02 ± 0.18 for 0 CTL escapes vs. 0.74 ± 0.06 for ≥3 CTL escapes, ρ = −0.15, P = 0.067)." (PMID 30356083, 2018). "We found the frequency of T cell infection was higher in moDC-CD4+ T cell cocultures compared to moDC-PBMC cocultures, which is likely due to the inhibitory effect of CD8+ T cells on CD4+ T cell infection." (PMID 29293546, 2018). "The transmission risk ratio of EHI (CD4 >500 and/or RITA positive) relative to all other stages of infection is 3.70 (95% CI, 3.36–4.09)." (PMID 29506269, 2018). "By 8 days post infection CD4-depleted mice develop higher viral RNA (vRNA) titers in liver, spinal cord and brain than control mice, indicating that CD4+T cells were necessary to control virus replication in the liver and CNS." (PMID 30212537, 2018). "A similar pattern of protection against intranasal infection with mixtures of F.G.A and the virus was observed in both wild-type and CD4 knockout mice." (PMID 30200514, 2018).
infection (continued). "Survival of HIV positive patients on haemodialysis has been shown to be correlated with earlier stage of the infection, younger age, higher CD4 counts, and treatment with c-ART." (PMID 29976156, 2018). "We show that MCMV evades CD4+ T cells via its M78 protein, and that this helps infection to spread despite the immune response." (PMID 29447285, 2018). "Four patients with acute EVD demonstrated CD8+ and CD4+ T cell activation against several viral proteins, and this activation persisted for up to one month after infection." (PMID 29795572, 2018). "Given the causal relation between CD4+ cells and Provirus, SRS indicates the duration of the beneficial effects of a temporary cART administered at a given time post-infection." (PMID 30021018, 2018). "Interleukin-8 exhibits a potent chemotactic activity for neutrophils and studies also suggest that by chemoattracting neutrophils it indirectly induces CD4+ T lymphocyte migration toward the site of infection." (PMID 30568639, 2018). "An additional important feature shared by PRO and BRY is the potential to inhibit de novo infection by reactivated virus through the capacity to downregulate the HIV-1 receptor CD4 as well as CCR5 and/or CXCR4 co-receptors." (PMID 30008723, 2018). "The ability to measure (and predict) specific CD4+ responses is crucial for the understanding of pathological events, such as infection by pathogens or cancerous transformations." (PMID 30446001, 2018). "HIV dominantly infects CD4 T cells and significantly reduces their number immediately following infection during a time when the first antibody responses are developing in the host." (PMID 30161121, 2018). "We found that CD8 T cells form conjugates and kill HIV-infected CD4 T cells in all stages of the infection, including in HIV-infected patients on ART." (PMID 30254642, 2018). "At 60 h post-infection, Ezh2–/– Smarta CD4+ T cells were detected in recipient spleens in similar numbers as WT cells, and showed similar rate of Caspase-3/7 activation." (PMID 30575739, 2018). "HIV pathogenesis starts with the infection and replication of the virus in CD4+ T lymphocytes, macrophages and dendritic cells." (PMID 30481211, 2018). "The power of this approach was the association of TCR clonotypes to a specific gene expression profile that provided a detailed molecular description of the whole CD4+ T cell population and monitored the dynamics of CD4+ T cell subsets upon infection." (PMID 30072991, 2018). "Using a CD4 back-calculation model and date of entry into the UK, we estimate that approximately 500 black African heterosexuals acquired their infection each year in the UK over the 5 years (equating to 30% of all newly diagnosed black Africans)." (PMID 29924799, 2018). "Early studies revealed the covert infection of CD4 T cells in the LN and its role in the depletion of these cells throughout disease progress." (PMID 30319664, 2018). "We infer that the time from infection to CD4 measurement is a useful indicator for monitoring delays in access to HIV medical care among newly diagnosed PLHIV." (PMID 29895275, 2018). "On the other end, high baseline CD4+ T-cell counts (>500 cells/μL) were observed even in subjects that progressed rapidly after infection." (PMID 29342870, 2018). "Overall, using a median estimate of CD4 count at the time of infection, it was estimated that 53.2% (95% CI = 48.3–58%) of HIV infected foreign patients had acquired HIV after having arrived in French Guiana." (PMID 29420591, 2018). "Yet, interestingly, among all of the infants studied, there was a strong inverse correlation between the percentage of activated CD69+ CD4+ T cells in the peripheral blood at the time of the first challenge and the number of challenges to infection." (PMID 29359183, 2018). "On the one hand, a variety of stimuli including environmental factors, infection, inflammation, and autoimmune reactions induces autoreactive CD4+ T cells to be activated in the periphery." (PMID 30035132, 2018).
infection (continued). "Of interest, the X4-tropic HIV-1 HE strain showed rapid adaptation towards CXCR7-mediated infection after continuous passaging on CD4- and CXCR7-expressing cells." (PMID 29560468, 2018). "Ag85b240-254 elicits a CD4+ T cell response early after infection, but Mtb reduces Ag85b production within three weeks after in vivo infection." (PMID 29782535, 2018). "Herein, we report that immunization with LdCen−/− parasites produces more functional Th1-type CD4+ T cells via downregulation of CD200–CD200R immune inhibitory axis compared to wild-type infection." (PMID 29915577, 2018). "Ss infection is characterized by significantly increased absolute numbers of naïve and decreased absolute numbers of central and effector memory CD4+ T cells in comparison to UN individuals." (PMID 29795573, 2018). "S1 and S2 Tables show the overall country of origin of patients in Cayenne General Hospital outpatient clinic and the country of origin of patients with an available date of arrival and initial CD4 count at diagnosis used to compute the duration of infection." (PMID 29420591, 2018). "Under these conditions, MΦ-mediated trans infection of HIV-1 to autologous CD4+ T cells was detected in eight of 10 SN." (PMID 29643243, 2018). "Significant expansion of cytokine-producing CD4+ T cells in the MLNs was detected on days 7 and 14 after infection." (PMID 29317510, 2018). "We have recently reported that infection of mice with B. pertussis induce the development of CD69+CD103+/− CD4 TRM cells in the lungs." (PMID 30147701, 2018). "This location in sites of infection is important as local lung-resident memory CD4 T cells promote better protection than splenic memory CD4 cells against IAV infection." (PMID 29632538, 2018). "When comparing DNA damage in our groups, there was less oxidative damage in naïve patients with infection for more than five years and CD4+ T cell counts higher than 500 cells/mm3." (PMID 29992171, 2018). "The immunodominant antigen ESAT-6 retains high levels of expression throughout infection and elicits a dominant CD4+ T cell response in C57BL/6 mice." (PMID 29782535, 2018). "Lymphocytes T CD4+ cells (Jurkat) demonstrated low permissiveness to OROV, though being susceptible to infection in vitro, as denoted by the 20% of infected cells." (PMID 29813068, 2018). "CD4+ T cells play a key defensive role during the infection of parasites; they fully activate CD8+ T cells by destroying infected cells." (PMID 30236160, 2018). "The next highest scoring hit is SIGLEC1/CD169, an HIV attachment factor that has been characterized to facilitate trans infection of CD4 +T cells by DCs through binding to sialylated glycosphingolipids on the HIV particle." (PMID 30520725, 2018). "Specifically, we set out to enumerate pMHC-specific CD4+ T cells in adult and old mice after immunization or infection in order to evaluate how aging impacts their expansion." (PMID 29864157, 2018). "For the CD4+ cell count we find that there is only one phase of sustained response due to treatment that lasts up to 12 months post infection." (PMID 30021018, 2018). "Our finding that L-selectin shedding is required for HIV release either in experimental infections or from patient-derived CD4+ T cells reveals a novel pathway to suppress both active and latent viral release." (PMID 30026537, 2018). "Each infection resulted in an increase in both CD4 and CD8 TEM cells (p < 0.001), with the biggest increase in CD8 TEM in mice that received all three infections." (PMID 29963060, 2018). "We investigated the expression of glucose transporters (GLUT) and glycolytic enzymes in human CD4+ T cells in response to infection with HIV-1." (PMID 29518929, 2018). "This novel strategy also provides a new research pathway in which to examine activation of autoreactive CD4+ T cells after vaccination or natural infection." (PMID 30619245, 2018).